WNT2B (Wnt family member 2B)
Diseases named in the same sentence as WNT2B in open-access papers (continued):
Sharing a sentence is not in itself a finding about the gene and the disease.
inflammatory bowel disease (1 paper, 2025). A spectrum of small and large bowel inflammatory diseases of unknown etiology. "In a similar fashion, crosstalk between Wnt2b secreting fibroblasts and natural killer (NK) cells contributes to fibrosis in inflammatory bowel disease (IBD)." (PMID 40376615, 2025).
Insulin resistance (1 paper, 2019). Increased resistance towards insulin, that is, diminished effectiveness of insulin in reducing blood glucose levels. "WNT2B is a component of the Wnt signaling pathway, and this gene which activates the Wnt signaling pathway is responsible for the development of NIDDM but may be identified with insulin resistance." (PMID 30678306, 2019).
iris colobomas (1 paper, 2023). "Humans with WNT2B mutations exhibit neonatal-onset chronic diarrhea, and a variety of ocular abnormalities, including iris colobomas and corneal defects, although it is unclear whether WNT2B is directly responsible for these ocular pathologies." (PMID 37048106, 2023).
ischemic stroke (1 paper, 2023). A stroke disorder caused by obstruction of blood flow to the brain, due to thrombotic (local blood clot formation) or embolic (due to a blood clot or other material traveling from another site) event. "Additionally, WNT2B variants contribute to the susceptibility and occurrence of ischemic stroke, and WNT2B is associated with the clinical treatment response and clinical remission in depressed patients, indicating the potential of Wnt2b in neurological disorders." (PMID 36852442, 2023).
liver diseases (1 paper, 2017). "However, the role of Wnt2b in TLR4-associated hepatic inflammation and fibrosis-related liver diseases is still unclear." (PMID 28638086, 2017). "However, the significance of Wnt2b in the pathogenesis of fibrosis-related liver diseases remains undefined." (PMID 28638086, 2017). "And, the possible correlation between Wnt2b and TLR4 in the progression of fibrosis-related liver diseases will be continued in our future work." (PMID 28638086, 2017).
malignant pleural mesothelioma (1 paper, 2017). A malignant neoplasm that arises from mesothelial cells in the pleura and shows a diffuse growth pattern. "Intratumoural WNT2B was reported to be correlated with the expression of Survivin and c-Myc, tumour proliferation and prognosis in malignant pleural mesothelioma." (PMID 28053597, 2017).
mild cognitive impairment (1 paper, 2023). "And our study found Wnt2b decline in AD was associated with cognitive impairment and underlying mechanism for the first time." (PMID 36852442, 2023). "Our study highlights that Wnt2b decline is associated with cognitive impairment in AD, and upregulation of Wnt2b can exert neuroprotective effects in AD, particularly in ameliorating mitochondrial dysfunction." (PMID 36852442, 2023). "We will continue to study the effects of Wnt2b on mitochondrial and synaptic dysfunction and cognitive impairment in primary neurons and animal models in depth." (PMID 36852442, 2023). "What's more, although we detected differences in plasma Wnt2b level between the AD and cognitively normal groups, we will expand the sample size and enroll mild cognitive impairment subjects to further validate the relationship between plasma Wnt2b and cognitive function in AD." (PMID 36852442, 2023). "In summary, the present study mainly found decrease of plasma Wnt2b levels in AD patients, and canonical Wnt signaling and mitochondrial dysfunction might be potential mechanisms for Wnt2b involved in neuronal damage and cognitive impairment in AD." (PMID 36852442, 2023). "Especially, Wnt2b was found reduced in AD animal model without cognitive impairment at 6‐month‐old, suggesting Wnt2b might play an important role in the early pathogenesis and progression of AD." (PMID 36852442, 2023).
non-small cell lung carcinoma (1 paper, 2020). A group of at least three distinct histological types of lung cancer, including non-small cell squamous cell carcinoma, adenocarcinoma, and large cell carcinoma. "MiR-577 targets tumor-promoting gene WNT2B which mediates Wnt/β-catenin pathway to suppresses cell proliferation and epithelial-mesenchymal transition in non-small cell lung cancer." (PMID 32373535, 2020).
osteoporosis (1 paper, 2025). A condition of reduced bone mass, with decreased cortical thickness and a decrease in the number and size of the trabeculae of cancellous bone (but normal chemical composition), resulting in increased fracture incidence. "Secondary analysis further confirmed the potential association of WNT2B rs3737136, CFH rs12401515, and DNM3 rs1576340 with osteoporosis-related traits, but their association with RCTs was not replicated in the present study." (PMID 40866365, 2025).
renal cell carcinoma (1 paper, 2020). "The results showed that in addition to Wnt1 and Wnt2b, PORCN and other related genes have varying degrees of mutation in renal cell carcinoma, which may mean that PORCN and its related genes will play an important role in renal cell carcinoma." (PMID 32104684, 2020).
retinal degeneration (1 paper, 2023). Degeneration of the retina. "To summarize, in this study we observed ectopic rod photoreceptor nuclei unaccompanied by retinal degeneration in a strain of systemic Wnt2b deficient mice." (PMID 37048106, 2023).
small cell carcinoma (1 paper, 2020). A neuroendocrine carcinoma composed of small malignant cells which are often said to resemble "oat cells" under the microscope. "Wnt2bb was previously shown to function in the Wnt2b-mediated Wnt/beta-catenin pathway in small cell cancer and in other tissues." (PMID 32523947, 2020).
tongue cancer (1 paper, 2020). A malignant neoplasm affecting the tongue. "The acquired cisplatin resistance in tongue cancer cells was associated with the induction of WNT-2B and GLUT1 overexpression, and the knockdown of WNT-2B sensitized resistant cells to cisplatin treatment and reduced colony formation in vitro and tumor growth in vivo." (PMID 32183420, 2020).
uveitis (1 paper, 2018). An inflammatory process affecting a part of or the entire uvea. "Similarly, WNT2B (ENSP00000358698), WNT9A (ENSP00000272164), WNT4 (ENSP00000290167), and WNT2 (ENSP00000265441) all participate in the pathogenesis of uveitis through the regulation of urea cells, thus validating their strong relationships with uveitis." (PMID 30349554, 2018).
tumor (37 papers, 2016 to 2025). "The expression of Wnt2b, which is known to be upregulated by polarization-promoting factors in macrophages, contribute to the polarization of tumor-associated macrophages." (PMID 39224599, 2024). "And WNT2B mRNA/protein overexpression was also associated with tumour T classification, clinic stage and lymph node metastasis (P < 0.05)." (PMID 28053597, 2017). "Extracellular vesicles (EVs) released from uniSTING-treated tumour cells contribute to dendritic cell sensitization, while combination therapy with α-Wnt2b antibodies shows synergistic inhibition of tumour growth and prolonged animal survival." (PMID 38831199, 2024). "The results of WNTs’ mRNA level assessment in the MSCs of the tumor niche in MM suggest possible prospects for mRNAs of WNT2B, WNT9B and CTNNB1 as being molecular prognostic markers that can predict the outcome of the disease." (PMID 37239457, 2023). "WNT2 and WNT2B produced by the tumor microenvironment had high expression in the classical subtype tumors, but low expression in the squamous subtype." (PMID 35536676, 2022). "Inhibition of Wnt2b or β-catenin suppressed the glycolysis of TAMs and reversed its tumor-promoting effects." (PMID 33407720, 2021). "Wnt2b/β-catenin/c-Myc signaling pathway plays an important role in tumorigenesis, tumor metastasis and the EMT process." (PMID 34750351, 2021). "In light of our findings, exosomal Wnt2B promotes an altered stromal compartment in the tumor, we next characterized the functional properties of exosomal Wnt2B-activated CAFs." (PMID 33731705, 2021). "As a potential target of tumour therapy, Wnt2b can not only promote malignant formation of tumour cells, but also play an important role in the formation of an immunosuppressive tumour microenvironment." (PMID 33407720, 2021). "Several Wnt genes were induced by MAPKi treatment in BPN tumor cells, including Wnt2b, Wnt4, Wnt8b, and Wnt10b." (PMID 33821796, 2021). "Subcutaneous model revealed that tumor growth was significantly increased in mice co-injected with CC cells and NFs pre-treated by SiHa-Wnt2B/Hela-Wnt2B/ME180-Wnt2B compared with SiHa-NC/Hela-NC/ME180-NC pre-treated groups or the control groups." (PMID 33731705, 2021). "Increased α-SMA expression was positively correlated with increased tumor Wnt2B expression (r = 0.6879, P < 0.0001)." (PMID 33731705, 2021). "As an important downstream target gene of β-catenin, c-Myc is involved in Wnt2b/β-catenin signal transduction and acts as a key regulator of glycolysis in tumour cells." (PMID 33407720, 2021). "We first identified an oncogenic lncRNA AC104041.1, which as a ceRNA for miR-6817-3p, mediates tumor growth and metastasis by regulating Wnt2B and consequently activating the Wnt/β-catenin pathway." (PMID 32826863, 2020). "The expression levels of Wnt2B, Wnt3A, Wnt6, Wnt8B and Wnt10B were significantly higher in primary liver tumor tissues than which in adjacent non-tumor tissues." (PMID 30814912, 2019). "We also observed specific interaction between fibroblasts and malignant tumor cells through the interaction of WNT5B and WNT2B with its downstream receptor in the WNT signaling pathway, which has been linked to supporting tumor cell proliferation, metabolism, and metastasis." (PMID 40874228, 2025). "Furthermore, it has been observed that Wnt2B released from exosomes of tumor cells positively regulates α-SMA and FAP expression in vitro and in vivo and these acquire a greater capacity for proliferation and migration." (PMID 38606999, 2024). "Additionally, high expression of HDAC3 correlates with a low expression of miR-376-3p and high expression of WNT2b, and strong HDAC3 expression is associated with tumor grade, tumor infiltration depth, LNM, and tumor stage in GC." (PMID 36358890, 2022).
tumor (continued). "Some tumours can be suppressed by targeting Wnt2b in tumour cells." (PMID 33407720, 2021). "Moreover, our findings indicate that Wnt2B transfers directly from tumor cells to fibroblasts through exosomes, thereby upregulate the expression of α-SMA and FAP in vitro and in vivo, which is correlated with our initial clinical data." (PMID 33731705, 2021). "Although tumour suppression by targeting Wnt2b has been found in a variety of tumours, the role of Wnt2b—despite having an important role in the Wnt family—in HCC is still unknown." (PMID 33407720, 2021). "In addition, fluorescence colocalization staining analysis for the TMA of HCC patients also showed that the expression of Wnt2b in macrophages within the tumour tissues was higher than that in adjacent tissues." (PMID 33407720, 2021). "EMT was a classical mechanism of tumour invasion and metastasis, and we had confirmed that WNT2B could affect the expression of EMT biomarkers in previous study." (PMID 28053597, 2017). "All these studies highlighted the role of WNT2B on tumour malignant processes." (PMID 28053597, 2017). "On the other hand, ACSL5 may exert its specific tumor suppressor role in different types of cancer through promoting ceramide or Wnt2B palmitoylation." (PMID 27171439, 2016). "Interestingly, WNT2b and WNT5a are highly expressed in NSCLC cells and stromal cells and may induce the polarization of tumor-associated macrophages (TAMs) to M2 status to strengthen the tumor progression." (PMID 37486552, 2023). "In line with the previous work, we validated that microRNA-338-5p functioned as a tumor suppressor to hamper the development of NPC in vitro and in vivo by targeting its downstream target Wnt family member 2B (WNT2B)." (PMID 34268117, 2021). "Interestingly, these activated fibroblasts are in turn able to promote tumor growth and aggressiveness, thereby forming a positive feedback loop to strengthen the cancer progression, and providing evidence of CAFs activated by exosomal Wnt2B possessing tumor-promoting functions." (PMID 33731705, 2021). "In this study, we first found that the expression of Wnt2b was upregulated in HCC-TAMs, and these tumour-promoting M2-like macrophages promote the proliferation, migration, and EMT of HCC." (PMID 33407720, 2021). "Tumour cells and different HCC-TAMs were injected via subcutaneously into immunodeficient mice to assess the effects of CpG ODN, Wnt2b, or β-catenin on HCC-TAMs in tumour growth in vivo." (PMID 33407720, 2021). "Previous studies demonstrate that miR-577 is a well-recognized tumor suppressor and it negatively regulates a lot of oncogenes and oncogenic pathways, including Sphk2, Smurf1, Rab14, Rab25, LRP6, β-catenin, Wnt2b, and so on." (PMID 33069244, 2020). "WNT2B was known to stimulate the canonical WNT/β-catenin pathway and affected various malignant tumour progression." (PMID 28053597, 2017). "Other ligands of the network include WNT2B, WNT5A, and WNT9A, differentially expressed by tumor cells and TAMs." (PMID 27215396, 2016). "Additionally, the levels of β-catenin, WNT2B, and WNT10A were elevated in tumor specimens derived from lincROR overexpression group." (PMID 39546475, 2024). "In addition, in our results, the transcriptional expression of WNT2B is divergent in LUAD and LUSC patients, implying the different roles of WNT2B in tumor progression in LUAD and LUSC." (PMID 35957916, 2022). "Accumulating evidence reveals that miR-449b-5p serves as a tumor suppressor by suppressing various cellular factors, such as yin and yang 1 (YY1), cell-cycle related and expression-elevated protein in tumor (CREPT), and Wnt family member 2B (WNT2B)." (PMID 34298879, 2021). "Since circ_0058106 binds miR-185-3p and regulates miR-185-3p expression, we speculated circ_0058106 may promote HSCC cells tumorigenesis, tumor metastasis and EMT process by regulating Wnt2b/β-catenin/c-Myc pathway via miR-185-3p." (PMID 34750351, 2021).
tumor (continued). "In addition to silencing Wnt2b or β-catenin expression, TLR9 agonist CpG ODN downregulated the level of glycolysis and inhibited the M2 polarization of HCC-TAMs, reversing the tumour-promoting effects of TAMs in vitro and vivo." (PMID 33407720, 2021). "Subsequently, compared with mice inoculated with a mixture of SMMC-7721 cells and TAMs that were transfected with a vector, we found that tumour growth rate and tumour load were remarkably reduced in mice inoculated with a mixture of SMMC-7721 cells and TAMs that had either silenced Wnt2b or CTNNB1." (PMID 33407720, 2021). "By further integrating the gene expression profiling data of AC104041.1, miRNAs and mRNAs in tumor and the sequence features of RNAs, we showed that AC104041.1 functions as a ceRNA for miR-6817-3p in the cytoplasm to increase Wnt2B stability and activate the Wnt/β-catenin pathway." (PMID 32826863, 2020). "Moreover, we measured circRNA-SORE expression in our collection of HCC tumor samples and found that the immunohistochemistry score of β-catenin was significantly correlated with the expression of circRNA-SORE, indicating that circRNA-SORE could regulate Wnt2b/β-catenin signals." (PMID 33222692, 2020).
cancer (36 papers, 2008 to 2025). A tumor composed of atypical neoplastic, often pleomorphic cells that invade other tissues. "Considering these results, we concluded that HFD stimulates colonic MSC expansion, Wnt2b production, and cancer-associated properties." (PMID 34971821, 2022). "One notable characteristic of the carcinoma tumors was high expression of Wnt2b and Fzd9, which cause distinct activation of the canonical pathway, leading to increased transcription." (PMID 18811984, 2008). "Wnt2b has been studied in cancers or tumor‐related diseases, while Wnt2b is one of the most important components that can induce the particular developing pattern of the fetal hippocampus and related to neurogenesis, such as retinal ganglion cells." (PMID 36852442, 2023). "WNT2B is a key inducer of WNT signal transduction, and its abnormal expression is associated with the occurrence and development of human cancers." (PMID 35193668, 2022). "The gene expression patterns show that gene activities in canonical WNT ligand WNT2B-producing myofibroblasts, which are located adjacent to cancer cells, are also altered." (PMID 36463319, 2022). "Significantly enriched KEGG pathways, such as proteoglycans in cancer (DCN, LUM, WNT2B, HSPG2; p = 3.60e 04), were also mainly associated with downregulated proteins." (PMID 35340765, 2022). "WNT2B is involved in different cellular processes, including tumorigenesis, and WNT2B overexpression has been correlated with cancer progression and metastasis." (PMID 33690729, 2021). "Based on the previous report that Wnt2B expression was involved in the Wnt/β-catenin signaling pathway, which has a key role in cancer metastasis, the EMT process and self-renewal of cancer stem cells." (PMID 32826863, 2020). "For instance, the Wnt2B gene is in a chromosomal region known to be deleted and rearranged in a variety of cancers." (PMID 20824140, 2010). "Silencing Wnt2b or β-catenin inhibits cancer cell glycolysis and EMT." (PMID 38994113, 2024). "To investigate whether Wnt2B secreted by cancer cells is present in the serum of patients with CC, we isolated and characterized exosomes from the serum samples of patients with CC (FIGO 2018, stage I–II, n = 8) and from healthy controls (n = 4)." (PMID 33731705, 2021). "Finally, our data showed that the inhibiting effects of microRNA-338-5p overexpression on NPC development were abrogated by upregulating WNT2B, suggesting that microRNA-338-5p targeted WNT2B to suppress cancer progression in NPC." (PMID 34268117, 2021). "Wnt2b was found dysregulated in several cancers with aberrant Wnt/β-catenin pathway activity 49-53." (PMID 34803507, 2021). "Studies have shown that Wnt2b is overexpressed in various cancers." (PMID 31130856, 2019). "In addition to WNT5A, WNT16 and WNT2B also produce alternative transcripts that are differentially expressed in human tissues and cancers." (PMID 24260410, 2013). "It is worth mentioning that in the existing studies, WNT7A and WNT2B played different roles in the prognosis of different cancer types, which may be attributed to their various mechanisms of action in diverse cancer cell lines and the activated signaling pathways." (PMID 35957916, 2022). "Moreover, ChIP-chip assays yielded a total of 48 genes enriched in at least three of the seven primary samples including genes associated with cell cycle such as ARGHEF2, CCNA2, CDKN2D, GAK2, ORCL6, PCPNP, and TACC1 and genes associated with cancer such as AR, AXIN2, IKBKG, ETS1, PTPN11, and WNT2B." (PMID 23300998, 2013). "Our data annotated 17 WNTs and found that WNT2B, WNT10A, WNT5A and WNT7B showed a similar cancer-positive pattern, and WNT7B was the most significant one." (PMID 35850748, 2022). "Exosomal Wnt2B secreted by CC cells promotes CAF conversion by activating the Wnt/β-catenin signaling, which further contributes to stroma remodeling and cancer progression." (PMID 33731705, 2021).